TNF (tumor necrosis factor)
Diseases named in the same sentence as TNF in open-access papers (continued):
Sharing a sentence is not in itself a finding about the gene and the disease.
cancer (continued). "CD8+ T cells either took place directly via synaptic exocytosis of cytotoxic granules that contained perforin and granzymes into the target cells or caused the indirect destruction of cancer cells through secreting cytokines, such as IFN-γ and TNF." (PMID 36263174, 2022). "By producing cytokines, including TNF-α, IL-12, and IL-6, M1 macrophages have an anti-cancer effect, but M2 macrophages promote the proliferation of cancer cells by producing IL-10, TGF-α." (PMID 36298592, 2022). "TNF-α generates the invasiveness of cancer and metastasis of cancer through triggering signaling pathways such as MAPK, which induces EMT." (PMID 36146567, 2022). "Th1 cells produce IFN-γ and TNF-α, which are important for the defense against intracellular bacteria, viruses, and cancer cells." (PMID 36431972, 2022). "Because of the potential tumorigenic effects of TNF, a few trials have investigated the use of infliximab, a TNFi, for the treatment of advanced cancer." (PMID 36081549, 2022). "TNF-α and other proinflammatory cytokines have been proven to be expressed based on C3a–C3aR signal transduction, and TNF-α is reported to have controversial roles in cancers; several studies have shown that it has protumor functions." (PMID 35725556, 2022). "Since such a balance is disrupted in a diseased cell in a cancer or autoimmune milieu, its restoration using interventional therapeutic approach involving TNFα is being considered recently." (PMID 36240239, 2022). "Experimental investigations implemented to examine the biological activity of the cell-free synthesized human TNF-α protein confirmed its significant anticancer potency and selective cytotoxicity against test cancer cell lines." (PMID 35205024, 2022). "Vitamin B6 levels decrease with increasing levels of inflammatory markers such as interleukin-6, C-reactive protein, and the alpha tumor necrosis factor which are involved in cancer." (PMID 35399658, 2022). "Several studies have shown that an increase in TNF-alpha expression induces cell survival and cancer progression." (PMID 35260587, 2022). "Here, we applied RNA seq technology to an established in vitro model of IC/BPS consisting of TNFα-treated cancer RT4 urothelial cells to characterize the overall effect of an inflammatory environment on their phenotype with genome-wide resolution." (PMID 36045687, 2022). "In response to ROS produced by cancers, the innate immune system is activated, where macrophages and dendritic cells produce proinflammatory cytokines such as tumor necrosis factor (TNF-α) and Interleukin-1β (IL-1β) to enhance adaptive immunity." (PMID 36503580, 2022). "Based on previously published data and the results of our study, we suggest that the use of MUC1 and MAGE-A3 in combination with TNF-α is a more reliable approach to generate autologous dendritic cells for basic research on cancer immunology." (PMID 35589776, 2022). "This view is supported by the observation that the anti-cancer activity of low-dose NGR-TNF in murine models is abrogated by co-administration of a neutralizing anti-CD13 antibody or by anti-TNF-Rs antibodies." (PMID 35890309, 2022). "Another marker deemed essential in cancer resistance is TNF-α, which is a proinflammatory cytokine that exaggerates cellular inflammation, proliferation, and carcinogenesis in MCF-7 cells." (PMID 35011526, 2022). "Tumor necrosis factor (TNF)-stimulated nuclear factor-kappa B (NF-κB) signaling plays very crucial roles in cancer development and progression, and represents a potential target for drug discovery." (PMID 35222445, 2022). "Recently, some researchers believe that TNF-α plays a role in carcinogenesis by activating the nuclear factor kappa-light-chain-enhancer (NF-κB); the latter plays an important role in expressing cancer-related genes." (PMID 35928364, 2022). "TNF, also known as TNFα, is a cytokine that has the ability to both induce and inhibit cancer cell growth." (PMID 35563397, 2022).
cancer (continued). "High cancer recurrence risk among obese survivors can be driven by inflammatory cytokines, including C-reactive protein (CRP), Interleukins −3, −6, and −8 TNF-α." (PMID 35276833, 2022). "The mRNA and protein expression of TNF have been detected in malignant and stromal cells from human cancer biopsy samples; moreover, plasma TNF levels have been found to be increased in some patients with cancer, notably those with poor prognosis." (PMID 36613819, 2022). "Knockout of key autophagy-related genes sensitizes cancer cells to TNF-induced death and TNF-mediated T cell cytotoxicity." (PMID 35401556, 2022). "For instance, cancer promotes the expression of TNF-α (a pro-inflammatory factor), which can downregulate the transcription of the albumin gene and inhibit albumin synthesis in hepatocytes." (PMID 35719922, 2022). "In the early stage of PAAD, M0 macrophages exhibit antitumor property by secreting TNF-α to induce the cell cycle arrest and apoptosis of cancer cells." (PMID 35083488, 2022). "Due to systemic toxicity these were, however, terminated and TNF is now only approved in a loco-regional setting as a cancer therapeutic." (PMID 35432372, 2022). "The undesirable effect of high‐dose Z‐vad was also reported in the previous studies, and it was suggested that a high‐dose of Z‐vad paradoxically augmented cell death in TNF‐α‐treated neutrophils and in cancer cell lines." (PMID 35315192, 2022). "This work identifies that YAP is critical to drive several biological effects of TNF which are involved in cancer and inflammatory disorders." (PMID 35401557, 2022). "It was observed that IC50 values of cell-free synthesized human TNF-α against test cancer cell lines were significantly (p < 0.05) lower than that against PBMCs." (PMID 35205024, 2022). "In cancer cells, TNF-α was found to induce the Warburg effect, increasing aerobic glycolysis, ATP production, and lactate secretion and decreasing oxidative metabolism." (PMID 36555705, 2022). "Our results show that TNFα-stimulated NPU cells exhibit similar changes in their phenotype as TNFα-stimulated RT4 cancer urothelial cells." (PMID 36045687, 2022). "On the contrary, TNF-α and other factors secreted by cancer cells can stimulate the skeleton rearrangement of endothelial cells, making them shrink and form gaps, so that cancer cells can more easily pass through and reach target organs." (PMID 36430215, 2022). "αROR1-CAR T cells can be activated by ROR1-ScFv conjugation, releasing cytokines including IL-2, IFN-γ, and TNF-α and inducing cytotoxicity in cancer cells." (PMID 35484298, 2022). "It is well known that TNF-α is a pro-inflammatory cytokine, which displays both apoptotic and anti-apoptotic properties in cancer cells, depending on the nature of the stimulus and active status of certain signaling pathways." (PMID 36417428, 2022). "TNF-α and IL-6 are multifunctional cytokines involved in chronic inflammation and contribution to the progression of cancer." (PMID 35444660, 2022). "For example, expression of TNFα was elevated in hearts from mice with cancer and correlated to an increasing concentration of sTNFR1 in serum." (PMID 35309730, 2022). "Cancer metastasis suppression experiments using anti-TNF antibodies have been verified by single or combined treatment in various cancer types since they were first reported in 1993." (PMID 36613819, 2022). "TAK1 inhibition in cancer cells in vitro has shown an increase in apoptosis through the inhibition of TNF survival and inflammatory signaling." (PMID 36176271, 2022). "This review illuminates what caused this misunderstanding and answers the question if there is any connection at all between the cytokine Tumor Necrosis Factor and cancer." (PMID 36358688, 2022).
cancer (continued). "IL-6 is one of the candidates that can cooperate with TNFα or act alone as a mediator of systemic inflammation in cancer cachexia." (PMID 36078078, 2022). "Next, we validated the effect of ouabain and the related cardiac glycoside digoxin on kynurenine production in TNF/IFN-ɣ-stimulated cancer cell lines." (PMID 35150740, 2022). "Anamorelin (appetite stimulation), megestrol acetate, eicosapentaenoic acid, phytocannabinoids, targeting MSTN/activin, and molecules targeting proinflammatory cytokines, such as TNF-α and IL-6, are being tested as treatment options for cancer cachexia." (PMID 35565236, 2022). "It has been shown that low-dose chronic TNF-α production is a feature of many cancers during which TNF-α promotes cancer growth, invasion, and metastasis through different mechanisms." (PMID 36376825, 2022). "TNF-α can induce apoptotic cell death, but yet many cancer cells are resistant to this action due to activating NFκB-regulated gene products or NFκB-mediated cellular processes." (PMID 36619302, 2022). "This included the TNF-related apoptosis-inducing ligand (TRAIL/TNFRSF10), which further supports a role for FcεRI-release of TNF-α from MCs that induces apoptosis of cancer cells." (PMID 35574362, 2022). "The subgroup analysis by age group, sex, type and duration of TNF inhibitor and nbDMARD used, disease duration, and time to event in the matched cohort revealed that the adjusted HRs for cancer consistently tended to be lower in the TNF inhibitor cohort." (PMID 35945635, 2022). "CTLs also secrete interferon-γ (IFN-γ) and tumor necrosis factor α (TNFα) to trigger cytotoxicity in cancer cells." (PMID 36291797, 2022). "With this discovery, they demonstrated that SSD has a significant potential to be developed as a combined adjuvant therapy for cancer patients with TNF-α." (PMID 36547471, 2022). "The transcriptional mis-regulation in cancer, TNF, T cell receptor, PI3KAkt, and lysine degradation signaling pathways were evaluated for DE source genes and found to be associated with cattle-bull reproduction." (PMID 36553452, 2022). "Pegylated colloidal gold nanoparticles conjugated to tumor necrosis factor-alpha (TNFa) particles for cancer therapy and silicon nanocarriers for parenteral peptide administration, for example, are in early clinical development." (PMID 35957103, 2022). "Numerous cytokines such as IL-6, IL-10, IL-23, TNF-α, and TGF-β were found to be associated with carcinogenesis and the development of cancers, functioning as pro- or anti-tumorigenic." (PMID 36140470, 2022). "From the outcome of the present study, it was found that physical exercise can reduce cancer incidence by improving immunity markers such as TNF-α, IL-6, IL-10, and NK cells." (PMID 35935260, 2022). "We recommend that IAP antagonist therapy should be postponed to the condition that host microbiota and levels of serum TNFα and LPS are restored to normal for those cancer patients who take antibiotic therapy." (PMID 36119107, 2022). "A significant increase (p < 0.01) in the levels of CRP and TNF-α was observed in both categories of cancer patients compared to the healthy individuals." (PMID 35692834, 2022). "TNF-α can also induce ROS production by the mitochondria, contributing to the redox imbalance and mitochondrial dysfunction in cancer cachexia." (PMID 35204066, 2022). "It is now widely accepted that inflammatory responses, regulated by various pro-inflammatory cytokines, including tumor necrotic factor-α (TNF-α), play an important role in cancer development and progression." (PMID 36555705, 2022). "Our previous work has described the correlation between elevated levels of serum cytokines IL-6 and TNF-α in the cancer progression and grading changes in localized PCa, showing the great potentiality of cytokines to impact cancer diagnostics." (PMID 36059480, 2022).
cancer (continued). "Oncology research has shown that multiple angiogenic proteins and their receptors show increased expression triggered by cancer-related hypoxia and inflammatory cytokines, such as tumor necrosis factor alpha (TNF-α) and interleukin-6 (IL-6)." (PMID 35741001, 2022). "Even though there is a body of evidence regarding the association of ADIPOQ and TNF-α, only a few studies have addressed the relationship between this immune mediator and ADIPOQ receptors, especially in cancer." (PMID 36429712, 2022). "Activated macrophages released large amounts of inflammatory cytokines, e.g., COX-2, TNF-α, IL-6 and plasminogen activator inhibitor-1 (PAI-1), aggravating the state of chronic inflammation and enhancing insulin resistance and the risk of cancer initiation." (PMID 35328822, 2022). "In contrast, NFκB that is induced by drug treatments has been shown to augment necroptosis when inducing the production of autocrine TNF by cancer cells." (PMID 35625711, 2022). "Specifically, poor sleep can suppress the immune system, cause alterations in the methylation of inflammatory genes such as IFN and tumor necrosis factor (TNF), as well as upregulate cancer-stimulatory cytokines." (PMID 36139643, 2022). "Interactions between TNF with TNF-R1 activate the NF-κB signaling pathway, which plays important roles in cancer development and progression." (PMID 35222445, 2022). "Accordingly, the inhibition of cytokines such as tumor necrosis factor alpha (TNF-α) or interleukin (IL)-1 reduces metastatic spread to the lung in vivo, and elevated cytokine serum levels indicate an unfavorable outcome of cancer patients." (PMID 35031433, 2022). "Tumor necrosis factor (TNF) family members play vital roles in cancer development and antitumor immune responses." (PMID 36313549, 2022). "TNFα is frequently synthesized from activated macrophages, which have been localized to adipocyte stores in weight-losing cancer patients." (PMID 36078078, 2022). "GSDMB can also be upregulated by different chemokines (IFN-α, -β, and -γ, or a lesser extent TNF–α) in cancer models, and methotrexate in gut epithelium, but the effects of this upregulation depends on the cellular and pathological settings." (PMID 36163066, 2022). "We found that the upregulated cancer-related genes were mainly enriched in several signaling pathways including the TNF signaling pathway, NOD-like receptor signaling pathway, and NF-κB signaling pathway." (PMID 36578029, 2022). "Cytokines like tumor necrosis factor-α (TNF-α) and IL-1β can also promote the proliferation of cancer cells." (PMID 35645817, 2022). "Substantial experimental and clinical data have been shown that TNF-α is involved in the promotion and progression of cancer." (PMID 36591235, 2022). "Through the inhibition of cIAP, SMAC mimetics have been found to sensitise cancer cells to TNF-induced cell death both in vitro and in vivo." (PMID 35401556, 2022). "During cancer cell invasion, inflammatory cytokines, mainly TGFβ, TNFα and IL-6, activate transcription factors such as Smads, NF-κB and Snail, driving EMT forward." (PMID 35884845, 2022). "The salivary and serum concentrations of chemerin, α-defensin 1, and TNF-α were significantly higher in cancer patients compared to the control group." (PMID 36005576, 2022). "A systematic review of 34 studies showed that IL-6 and TNF were associated with the severity of oral mucosal tissue damage in patients with cancer; the most investigated cytokines were IL-6, TNF, and IL-10." (PMID 35476641, 2022). "Cancer-induced changes in circulating factors, such as IL-6 and tumor necrosis factor-α (TNF-α), contribute to increased adipose lipolysis in CAC, possibly through modulating ATGL." (PMID 35684106, 2022). "Depletion of FAP-expressing CAFs can cause hypoxic necrosis of cancer and stromal cells via interferon-γ (IFN-γ) and tumor necrosis factor-α (TNF-α)." (PMID 35681617, 2022).
cancer (continued). "In contrast, another group demonstrated that FoxL1 can activate the same pathway by promoting the induction of tumor necrosis factor (TNF) related apoptosis-inducing ligand (TRAIL) in cancer cells." (PMID 35743818, 2022). "The comparatively lower TNF-α levels seen in the M1 plus cancer cells compared to the high levels of TNF-α in the M1 macrophages alone is likely secondary to the difference in time points (24 vs 48 hrs) and experimental methodology." (PMID 36713536, 2022). "Tumor necrosis factor (TNF)-related apoptosis–inducing ligand (TRAIL) induces apoptosis in cancer cells." (PMID 35385679, 2022). "Meanwhile, this activated signaling pathway can promote the transcription and synthesis of TNF-α, which in turn leads to more serious cancer pain." (PMID 35719369, 2022). "TNF-α promotes the activation, differentiation, survival, or death of cancer cells under specific conditions." (PMID 36140220, 2022). "Many cancer cells constitutively secrete picogram quantities of TNF, and host cells, such as myeloid cells, also produce TNF." (PMID 35844550, 2022). "Immunosuppression is a risk factor for NTM infections, particularly in patients with HIV, patients with organ transplants, cancer patients, or biologic treatment, especially patients using anti-TNF therapies." (PMID 35410188, 2022). "Interleukin 1 (IL-1) and tumor necrosis factor α (TNF-α) are considered key molecules for cancer progression." (PMID 35732709, 2022). "With cytokines such as the IL-1β, IL-6, and TNF all having pro-angiogenic properties, it is clear that inflammation and angiogenesis are related to cancer." (PMID 35626056, 2022). "For instance, Th1 lymphocytes secrete IFN-γ and TNF-α to provoke senescence in their recipient β-cancer cells, thereby retarding tumor growth." (PMID 36611926, 2022). "In cancer cachexia, various cytokines, such as TNF-α and IL-6, promote the lipolysis of triglycerides in WAT." (PMID 36072935, 2022). "On the other hand, TNF-α derived from macrophages stimulates caspase-8 expression in cancer cells, which further specifically lyses GSDMC into N-GSDMC to induce pyroptosis." (PMID 35990696, 2022). "The results of KEGG pathway enrichment analysis showed that genes were mainly enriched in the PI3K-Akt signaling pathway, IL-17 signaling pathway, TNF signaling pathway, apoptosis and other pathways in addition to various cancer pathways." (PMID 36699068, 2022). "Increased inflammation as a long-term side effect of cancer chemotherapy and irradiation is well documented, and the release of TNFα from mononuclear cells is known to result in endothelial cell damage following irradiation." (PMID 35954226, 2022). "Sequestration of TNF has been tested in Phase I and II clinical cancer trials with TNF antagonists as single agents." (PMID 35879777, 2022). "TNFα mediates cancer cachexia in adipose tissue by decreasing the expression of glucose transporter 4 (GLUT4), which in turn inhibits glucose transport and lipogenesis." (PMID 35441960, 2022). "For pathway analysis, the common genes were particularly enriched in pathways in cancer, proteoglycans in cancer, T cell receptor signaling pathway and TNF signaling pathway." (PMID 35637248, 2022). "Earlier studies have reported that FK866 is a NAMPT inhibitor and controls cancer progression by a downregulation of TNFα, IL-6 expressions, CXCR4." (PMID 36497496, 2022). "A previous study showed that K-80003 exerts anti-cancer effect by inducing TNFα-dependent apoptosis." (PMID 34410548, 2022). "TNF-α, C-reactive protein (CRP), and serum soluble interleukin-2 receptor (sIL2r) have also been associated with MDD in patients with cancer, directly modulating the HPA axis." (PMID 36185233, 2022). "Cytokines transforming growth factor (TGF)-β1 and tumor necrosis factor (TNF)-α are potent inducers of EMT in many cancers." (PMID 35163489, 2022). "A Phase 1 study of the anti-TNF antibody infliximab reported disease stabilization in 7 out of 41 patients with progressive cancer." (PMID 36613819, 2022).